LBP (lipopolysaccharide binding protein)
Diseases named in the same sentence as LBP in open-access papers (continued):
Sharing a sentence is not in itself a finding about the gene and the disease.
Sepsis (continued). "These two functions might help to explain that either LBP blockade or G-CSF treatment alone was not useful in the therapy of patients with severe sepsis." (PMID 26798659, 2015). "In contrast, although a higher LBP concentration was found in infected than in non-infected patients, a correlation between LBP and sepsis mortality could not be detected in another study." (PMID 23398965, 2013). "These two functions might help to explain that determination of LBP levels alone was not useful as biomarker of the severity of sepsis." (PMID 23437199, 2013). "Furthermore, LBP and CRP plasma levels have quite the same predictive value and are neither suitable to monitor resolution of sepsis nor sufficiently reliable to detect a recurrent infection during the first 14 days of sepsis in adult postoperative patients." (PMID 21901123, 2011). "Lipopolysaccharide (LPS), the Gram-negative bacterial outer membrane glycolipid, induces sepsis through its interaction with LPS-binding protein (LBP) or CD14 prior to subsequent formation of a complex with myeloid differentiation protein-2 (MD-2) and Toll-like receptor 4 (TLR4)." (PMID 19816595, 2009). "Despite evidence that females and males differentially respond to LPS, potentially due to variations in the upregulation of circulating LBP levels, no study has performed a sex-specific analysis of LBP in human SIRS/sepsis patients." (PMID 39997462, 2025). "The assessment of sepsis biomarkers showed that SIRS patients with detected pathogens in blood specimens had elevated PCT, LBP and CRP levels compared to non-bacteremic SIRS patients." (PMID 26986826, 2016). "The differences were not equal: median CRP and LBP levels in sepsis were about 1.5 to 2 times higher in sepsis, whereas median PCT and IL-6 were about 10 times higher in sepsis as compared to SIRS." (PMID 21687569, 2011). "Plasma concentrations of both LBP and CRP in nonsurvivors did not significantly differ from survivors and were rather lower than those in survivors during the first five days of sepsis." (PMID 21901123, 2011). "In the present study we compared the time course of LBP and CRP plasma levels in survivors and nonsurvivors during the first 14 days of postoperative sepsis and examined the performance of both markers regarding outcome prediction." (PMID 21901123, 2011). "The levels of LBP, IL-6 and CRP were statistically significantly higher among patients with sepsis compared to those infected but without SIRS (p < 0.001)." (PMID 20158885, 2010). "Levels of HMGB1, LBP, IL-6 and CRP in infected children without SIRS, with sepsis and with severe sepsis." (PMID 20158885, 2010). "The main aim of this study was to compare the levels of HMGB1, LBP, IL-6 and CRP between infected children without systemic inflammatory response syndrome (SIRS) and children with sepsis of different severity levels." (PMID 20158885, 2010). "In our study PCT performed poorer than CRP, IL-6 and LBP in diagnosing infection and in discriminating between noninfectious SIRS and sepsis/severe sepsis." (PMID 16569262, 2006). "Therefore, our finding that LBP and CRP concentrations in nonsurvivors increased above that of survivors only from day 7 to day 14, but not in the first three days, may rather be due to the relatively good homogeneity of our study group regarding sepsis severity at study entry." (PMID 21901123, 2011).
Obesity (69 papers, 2013 to 2026). Accumulation of substantial excess body fat. "Chronic stress causes upregulation of LBP, which functions to buffer ROS overload, potentially serving as a mechanism underlying stress-induced obesity." (PMID 38615060, 2024). "This decrease was associated with significant downwards trends in concentrations of C-reactive protein and lipopolysaccharide-binding protein, both notable inflammatory markers associated with obesity." (PMID 39184030, 2024). "Recent studies have shown the association between circulating LBP levels and conditions such as diabetes, obesity, and cardiovascular phenotypes." (PMID 39513871, 2024). "LGE, i.e. increased plasma levels of LPS and LPS-binding protein (LBP), is associated with obesity, diabetes, cardiovascular diseases (CVD), gut microbiome dysbiosis, and periodontitis." (PMID 35493525, 2022). "Correlation analyses in the replication cohort further underline the negative associations between inflammation and bacterial load and the association between LBP and inflammation as well as obesity." (PMID 34158092, 2021). "LBP and sCD14 are now recognized as clinical markers of endotoxin exposure and have been associated with obesity and metabolic disorders." (PMID 32570947, 2020). "We examined the association of plasma LBP concentrations with some parameters related to obesity and metabolic disorders in subjects from both the overfeeding and Lipinflox studies." (PMID 32570947, 2020). "Several studies in humans recently demonstrated that serum LBP levels are closely associated with obesity, the metabolic syndrome, and type 2 diabetes." (PMID 28486964, 2017). "Lipopolysaccharide-binding protein (LBP) has been reported to associate with metabolic diseases, such as obesity, diabetes, and non-alcoholic fatty liver disease." (PMID 28107471, 2017). "Recent evidence indicates the association of circulating LBP levels with obesity, diabetes, and cardiovascular diseases." (PMID 28486964, 2017). "The Chromosome 2 locus contains Ctnnbl1, a gene implicated in obesity and two interesting candidates, bactericidal/permeability-increasing protein (Bpi) and lipopolysaccharide binding protein (Lpb)." (PMID 26260972, 2015). "Thus, in this study, we aimed to evaluate LBP levels in relation to the presence of obesity and to investigate the association between circulating LBP and key metabolic disease parameters, including NAFLD, adipose tissue inflammation, and the presence of T2DM." (PMID 38139003, 2023). "LBP and sCD14 are closely linked to LPS and its activity and are also associated with obesity." (PMID 34828628, 2021). "Introducing a single bacterium that has been associated with obesity (Enterobacter cloacae) into germ-free mice led to weight gain, a disturbed glucose tolerance, higher systemic lipopolysaccharide binding protein (LBP) concentrations and lower adiponectin levels." (PMID 33178196, 2020). "In addition, it has been reported that high concentrations of serum LPS-binding protein (LBP) are associated with obesity, IRS and DM2." (PMID 30453950, 2018). "Ultimately LBP seems to be a marker of immune dysfunction and inflammation, though it has been linked to other systemic disorders including obesity and atherosclerosis, which may further account for its wide variability." (PMID 26388718, 2015). "Likewise, serum LBP concentrations were associated with obesity and related metabolic disorders in a selected sample of apparently healthy Chinese subjects." (PMID 23349936, 2013). "A. muciniphila levels are inversely associated to obesity and diabetes and its administration reduced body weight and metabolic inflammation by reducing plasma lipopolysaccharide (LPS)-binding protein (LBP) and leptin, as well as inactivated LPS/LBP downstream signaling." (PMID 30837951, 2019).
Obesity (continued). "Another study indicated that lipopolysaccharide-binding protein levels, a surrogate of inflammation immune responses, were associated with arterial stiffness among male patients with type 2 diabetes independently of obesity and traditional cardiovascular risk factors." (PMID 31684945, 2019). "Plasma LBP concentrations were also correlated with age, obesity, blood pressure, liver function, lipid metabolism, glucose metabolism, and inflammatory cytokines." (PMID 41745625, 2026). "Elevated plasma levels of zonulin and lipopolysaccharide-binding protein (LBP) are hallmarks of intestinal barrier dysfunction and are strongly associated with obesity-related inflammation and metabolic abnormalities." (PMID 41302175, 2025). "This study identified a causal association among LPS, LBP, NAFLD, and related metabolic disorders; LPS is a risk factor for NAFLD, obesity, HDL-c levels, and TG levels." (PMID 40388727, 2025). "Controlling the LBP pathway under oxidative stress shows promise for targeted interventions in stress-induced obesity and metabolic dysfunction, opening avenues for refined redox medicine in the future." (PMID 38615060, 2024). "In conclusion, our findings suggest that increased LBP expression results in not only fatty liver but also peripheral fat accumulation that leads to obesity." (PMID 38615060, 2024). "In contrast, RebD treatment was found to reduce adiposity, alleviate hepatic steatosis and lipid peroxidation, and decrease LBP, a marker of metabolic endotoxemia in a mouse model of diet-induced obesity." (PMID 38321177, 2024). "Lipopolysaccharide (LPS) and its binding protein LBP have emerged as potential contributors to the progression from overweight/obesity to overt metabolic diseases and NAFLD." (PMID 38139003, 2023). "Because the LPS signaling system is related to pathogenesis of obesity, we compared serum LPS and LBP." (PMID 37763997, 2023). "In this cross-sectional investigation, we evaluated circulating LBP in relation to obesity, NAFLD, visceral adipose tissue (VAT) inflammation, and type 2 diabetes (T2D)." (PMID 38139003, 2023). "Previous research reported that blood LPS concentration or blood LBP concentration was correlated with obesity, glucose metabolism, lipid metabolism, vascular function, liver function, and inflammatory conditions." (PMID 36837869, 2023). "Plasma levels of LBP (a recognized marker of metabolic endotoxemia in obesity) were significantly higher in the overweight group compared with the lean group (P = 0.005)." (PMID 37841878, 2023). "Lipopolysaccharide (LPS) seems to be involved in the transition of macrophages toward the inflammatory phenotype, and the LPS-binding protein (LBP) produced in response to microbial translocation is also a biomarker of obesity-related insulin resistance." (PMID 37174660, 2023). "After lean and obese Zucker rats were fed a casein control diet, SPC-LIF diet, or SPC-HIF diet for 18 weeks, liver TNF-α, MCP-1, iNOS, and LBP expression levels had significant interactions between diet and obesity status." (PMID 38075211, 2023). "In pharmacological experiments conducted in some studies, LBP of wolfberry has been shown to exert antiageing, antihyperlipidemia, obesity-improving, antifatigue, antitumour, antioxidation, and BMD-increasing effects." (PMID 35217917, 2022). "Enterobacter cloacae, which was intimately related to obesity, brought reduced adiponectin levels, elevated lipopolysaccharide binding protein (LBP) concentration, glucose tolerance disruption, and weight gain upon introduction into the germ-free mice." (PMID 36339448, 2022). "In humans, several studies have shown an increase in LPS and LPS-binding protein (LBP) in serum from patients with obesity, metabolic syndrome, or type 2 diabetes." (PMID 35631244, 2022). "LBP, a signal-transducing integral membrane protein that specially combined with LPS, has been reported to be a marker of obesity, insulin resistance, and “effective endotoxemia”." (PMID 34337024, 2021).
Obesity (continued). "The “weight loss” group also showed decreased levels of APOE, C5, CRP, LBP, NEGR1, and PRSS3, which have all been positively associated with obesity, inflammation, and metabolic disorders (22, –, 26)." (PMID 34519531, 2021). "The data from the current study for LBP/CD14 as an indicator of obesity agreed with previously published results." (PMID 31491976, 2019). "Studies showed that the endotoxemia-related biomarker, lipopolysaccharide-binding protein (LBP), is associated with obesity and fatty liver." (PMID 30458048, 2018). "The present study shown that higher LBP levels and inflammation are detected in the presence of obesity and in the presence of sleep-disordered breathing in a severity-dependent fashion." (PMID 29843666, 2018). "Lysozyme's co-localization in mouse intestine with LBP, an inflammatory marker found in obesity and other metabolic conditions, supports the potential role of lysozyme in inflammation." (PMID 28053879, 2017). "Serum LBP levels were positively correlated with the parameters of obesity, insulin resistance, and inflammation in our diabetic subjects, which is in agreement with observations from previous studies of non-diabetic populations." (PMID 28486964, 2017). "Alternatively, the association between serum LBP levels and aortic PWV can be explained by the indirect effects of LBP on aortic PWV via obesity and insulin resistance." (PMID 28486964, 2017). "Several studies suggest positive correlations between serum LBP level and metabolic disorders including IR, obesity, T2DM, and metabolic syndrome (MetS)." (PMID 26799617, 2016). "The miR883b-5p, which was upregulated by adiponectin and downregulated in human obesity repressed the LPS-binding protein (LBP) and TLR4 signaling, acting therefore as a major mediator of the anti-inflammatory action of ApN." (PMID 24741638, 2014). "Additionally, biomarkers of intestinal permeability, including LBP and zonulin, have been found at higher levels in individuals with obesity compared with controls." (PMID 41228453, 2025). "Some Blautia species (e.g., B. luti and B. wexlerae) are reported to have anti-inflammatory and anti-obesity effects, while others (e.g., B. producta) are negatively correlated with inflammatory markers like LPS binding protein (LBP), showing an opposite correlation with obesity." (PMID 39338443, 2024). "However, further investigation is required to fully understand the mechanism by which LBP modulates LDs and to which extent it contributes to LBP-mediated obesity." (PMID 38615060, 2024). "While no studies have explored toxins such as LPS in HS, increased levels of LBP in psoriasis and obesity may also be present in excess in HS." (PMID 37623895, 2023). "Circulating levels of LBP did not associate significantly with metabolic abnormalities in studies conducted in children and adolescents with obesity and in adult subjects, whose gut microbiota and short-chain fatty acid characterization was also available." (PMID 38139003, 2023). "Indeed, increased plasma levels of LPS and LPS-binding protein (LBP) are found in obesity and diabetes, and gut dysbiosis is involved in the pathogenesis of insulin resistance." (PMID 33600486, 2021). "Finally, expression of LBP (a marker of obesity and metabolic endotoxemia) was reduced by about 50% in both HIIT and MICT groups (p≤ 0.01 vs CONT)." (PMID 30964881, 2019). "Thus, although LPS/LBP-induced immune response is commonly involved in arterial stiffness, obesity, and insulin resistance, our results indicate that the LPS/LBP-induced innate immunity independently affects arterial stiffness in patients with type 2 diabetes." (PMID 28486964, 2017). "In conditions of obesity and coronary artery disease LBP expression is targeted by LXRs from macrophages, and serum LBP may serve as an important marker for atherosclerosis." (PMID 25652121, 2015). "Furthermore, chronic stress upregulates LBP expression, leading to insulin resistance and obesity." (PMID 38615060, 2024).
Obesity (continued). "A possible explanation for these findings is that hepatic LBP production may be triggered by chronic caloric excess and facilitate LPS degradation in the liver, thus protecting these individuals from the metabolic consequences of obesity." (PMID 38139003, 2023). "Furthermore, adipose-derived LBP directs local inflammatory and metabolic responses and may be an early biomarker for adipose tissue dysfunction in obesity." (PMID 37181127, 2023). "Therefore, strategies that suppress LBP expression in the liver or adipose tissue may alleviate inflammation and insulin resistance in obesity." (PMID 37181127, 2023). "However, growing experimental evidence may suggest that, in obesity, chronic endotoxemia stimulates LBP production, which facilitates LPS degradation in the liver." (PMID 38139003, 2023). "Several human studies showed that serum LBP levels increased in NAFLD, NASH, hepatitis C virus (HCV) infection, obesity, insulin resistance, metabolic syndrome and atherosclerosis." (PMID 30458048, 2018). "BMI-predictive proteins included established obesity markers and obesity-related proteins, including adiponectin, CRP, IGFBP1, IGFBP2, PRG4, SHBG, apolipoproteins (APOA4, APOF) and inflammatory response proteins (A2M, APCS, LBP, HSPG2, HP, AOC3, ITGB1, VNN1)." (PMID 39972214, 2025). "LBP mRNA was more highly expressed in individuals with obesity, regardless of diabetic status compared to lean individuals." (PMID 35933445, 2022). "Notably, circulating inflammatory biomarkers including plasma levels of both lipopolysaccharide-binding protein (LBP) and chemerin have been reported in patients with obesity." (PMID 33498461, 2021). "This raises the question as to which of the remaining 7/11 genes (LBP, RXRB, CPLX1, GLAK2, CSTL1, SLC9A3, CA12) may also have a role in obesity." (PMID 25651499, 2015). "Interestingly, feeding the mice a ketogenic diet with 90% saturated fat did not cause fatty liver or obesity in any of the LBPKI/KI, WT, or LBP−/− groups, which was consistent with our previous finding that LBP binds with PUFA-TG." (PMID 38615060, 2024). "Obesity-related metabolic disorders elicit systemic low-grade inflammation by increasing the levels of proinflammatory factors, such as monocyte chemoattractant protein-1 (MCP-1), CD11c, tumor necrosis factor-α (TNF-α), leptin, lipopolysaccharide binding protein (LBP), and interleukin-6 (IL-6)." (PMID 34579036, 2021). "However, it is noteworthy that the association between serum LBP levels and aortic PWV was independent of obesity, inflammation, and other traditional cardiovascular risk factors." (PMID 28486964, 2017). "Importantly, in this study, the relationship between serum LBP levels and aortic PWV was independent of traditional cardiovascular risk factors including age, obesity, renal dysfunction, hyperglycemia, and dyslipidemia." (PMID 28486964, 2017). "In this study, serum LBP levels were higher in PCOS subjects than in controls in both lean and overweight/obese individuals, suggesting that the association between LBP and PCOS is independent of obesity." (PMID 26799617, 2016). "HF-induced obesity was only prevented by the Lingon1 diet, whereas both batches of lingonberries reduced plasma levels of markers of inflammation and endotoxemia (SAA and LBP) as well as modified the composition and functionality of the gut microbiota, compared to the HF control group." (PMID 27125264, 2016). "Indeed, although LPS and LBP parallelly increase in obesity, LBP, unlike LPS, may exert protective effects against endotoxemia-mediated liver injury and, more generally, obesity-related metabolic complications." (PMID 38139003, 2023). "However, in the absence of obesity or diet-induced hepatic lipogenesis, liver-derived LBP appeared to have a protective function, helping to prevent liver inflammation, oxidative stress, and fibrosis, which suggests that inhibiting LBP could potentially amplify the proinflammatory effects of LPS." (PMID 41373509, 2025).
Obesity (continued). "Some classical inflammatory biomarkers, including CRP, SAA1, ORM1, and LBP, were determined to further confirm the notably lower inflammatory responses of IBD patients with overweight/obesity than those without overweight/obesity." (PMID 36759757, 2023).